TMPO (thymopoietin)
Description:
May help direct the assembly of the nuclear lamina and thereby help maintain the structural organization of the nuclear envelope. Possible receptor for attachment of lamin filaments to the inner nuclear membrane. May be involved in the control of initiation of DNA replication through its interaction with NAKAP95. Thymopoietin (TP) and Thymopentin (TP5) may play a role in T-cell development and function. TP5 is an immunomodulating pentapeptide. May be involved in the structural organization of the nucleus and in the post-mitotic nuclear assembly. Plays an important role, together with LMNA, in the nuclear anchorage of RB1. TP and TP5 may play a role in T-cell development and function. TP5 is an immunomodulating pentapeptide.
Synonyms: TP; LAP2; LEMD4; CMD1T; PRO0868
Tractability: Small molecule: a structure with a bound ligand is known. PROTAC: ubiquitination databases record sites on it; its protein half-life has been measured.
Gene: Protein-coding gene on chromosome 12 (98,515,561 to 98,550,351, forward strand). Ensembl gene ENSG00000120802.
Subcellular location: Nucleus; Chromosome; Nucleus inner membrane; Cytoplasm (Isoform Zeta)
Subcellular location (Human Protein Atlas): Nuclear membrane
Pathways (Reactome):
Signal Transduction: CDC42 GTPase cycle; RAC1 GTPase cycle; RAC2 GTPase cycle; RAC3 GTPase cycle; RHOA GTPase cycle; RHOC GTPase cycle; RHOD GTPase cycle; RHOF GTPase cycle; RHOG GTPase cycle; RHOJ GTPase cycle
Cell Cycle: Depolymerization of the Nuclear Lamina; Initiation of Nuclear Envelope (NE) Reformation; Nuclear Envelope Breakdown
Gene Ontology:
Molecular function: cadherin binding; protein binding; lamin binding; DNA binding
Cellular component: chromatin; nuclear membrane; nucleus; nuclear envelope; chromosome
Genetic constraint (gnomAD): Loss-of-function variants: 20 observed, 39.48 expected, observed/expected ratio (o/e) 0.51, 90% interval 0.35 to 0.74. The upper end of that interval is the gene's LOEUF score, 0.74, which puts it in group 3 of 6, group 1 being the genes least tolerant of losing a copy. Missense variants: 474 observed, 528.01 expected, observed/expected ratio (o/e) 0.9, 90% interval 0.83 to 0.97. Synonymous variants: 234 observed, 202.65 expected, observed/expected ratio (o/e) 1.15, 90% interval 1.04 to 1.29.
Gene-disease validity (ClinGen):
ClinGen rates the evidence that TMPO causes each of these diseases.
hypertrophic cardiomyopathy (autosomal dominant): Limited. A condition in which the myocardium is hypertrophied without an obvious cause.
Homologues: Orthologues: guinea pig TMPO (79% identical), tropical clawed frog tmpo (58% identical), dog TMPO (54% identical), macaque TMPO (54% identical), mouse Tmpo (51% identical), rat Slc25a3 (50% identical), pig TMPO (50% identical), zebrafish tmpoa (39% identical), zebrafish tmpob (30% identical), zebrafish lemd1 (22% identical), Caenorhabditis elegans emr-1 (11% identical). Paralogues in human: LEMD1 (9% identical).
Diseases named in the same sentence as TMPO in open-access papers:
TMPO is named in the same sentence as 49 diseases in open-access papers, as found by Europe PMC text mining. Sharing a sentence is not in itself a finding about the gene and the disease. The quoted sentences say what the papers report.
glioblastoma (8 papers, 2016 to 2025). The most malignant astrocytic tumor (WHO grade IV). "TMPO has been shown to induce proliferation and inducing cell cycle arrest and apoptosis in glioblastoma." (PMID 37182169, 2023). "According to the previous researches, TMPO has been reported as an oncogene in lung cancer, breast cancer, glioblastoma and so on." (PMID 32669970, 2020). "It has been demonstrated that knockdown of TMPO can significantly inhibit glioblastoma cell proliferation and arrest cell cycle progression at the G2/M phase 27." (PMID 31602262, 2019). "Comparing with normal brain tissues, TMPO expression in glioblastoma tissues is much higher as shown in three different microarray datasets including the Liang Brain dataset (n = 30, p = 0.015), the Murat Brain dataset (n = 80, p = 0.010), and the TCGA Brain dataset (n = 542, p = 1.29E−6)." (PMID 27756319, 2016). "Furthermore, the Sun Brain dataset revealed that TMPO was upregulated in glioblastoma tissues (n = 81, p = 2.22E−8) and oligodendroglioma tissues (n = 50, p = 2.25E−5) compared with normal brain tissues." (PMID 27756319, 2016). "Also, TMPO expression was significantly increased in glioblastoma tissues (n = 27, p = 0.002) and oligodendroglioma tissues (n = 3, p = 0.043) in the Shai Brain dataset." (PMID 27756319, 2016).
breast carcinoma (6 papers, 2016 to 2024). "For example, TMPO has been linked to breast cancer metastasis in clinical samples and tissue culture experiments, and its inhibition has been shown to impede the aggressiveness and metastasis in breast cancer by suppressing epithelial-mesenchymal transition (EMT)." (PMID 38233377, 2024). "Given the Lem-D transcripts, Ankle2, TMPO, Emerin, and Lemd2, were overexpressed in breast cancer patient samples and overexpression largely associated with poorer patient outcomes, we next investigated whether the Lem-D proteins were similarly overexpressed in TNBC cell lines." (PMID 38720803, 2024). "GENT2, TCGA, and KM plotter were utilized to investigate the expression and prognostic implications of several Lem-D proteins: Ankle2, TMPO, Emerin, and Lemd2 in publicly available breast cancer patient data." (PMID 38720803, 2024). "There is evidence to suggest that Ankle2, TMPO, Emerin, and Lemd2 expressions are correlated with breast cancer patient outcomes, but larger patient sample numbers are required to confirm this." (PMID 38720803, 2024). "Our data indicate that TMPO may be overexpressed in breast cancer tumors, as demonstrated by patient data and that the TMPOγ isoform protein is significantly increased in TNBC cell lines." (PMID 38720803, 2024). "However, statistical significance was not reached for the correlation between protein expression of TMPO and breast cancer patient OS." (PMID 38720803, 2024). "TMPO mRNA expression was negatively correlated with breast cancer patient OS." (PMID 38720803, 2024). "Thymopoietin (TMPO) has been demonstrated to be upregulated in various tumors, including lung cancer, breast cancer, and so on, but its role in GBM has not been reported." (PMID 27756319, 2016).
colon cancer (3 papers, 2022 to 2024). "The administration of 5-FU resulted in a time-dependent decrease in the expression of TMPO and an increase in the phosphorylation of c-Fos in colon cancer cells." (PMID 38233377, 2024). "Collectively, these data illuminated that 5-FU promoted the degradation of TMPO in colon cancer cells via the autophagic lysosomal pathway." (PMID 38233377, 2024). "Taken together, these findings revealed that TMPO-mediated phosphorylation of c-Fos conferred 5-FU resistance by regulating NANOG expression and promoting cell stemness in colon cancer cells." (PMID 38233377, 2024). "In this study, we found that 5-FU treatment triggers the autophagy-dependent degradation of TMPO and reduces its interaction with ERK1/2 in colon cancer cells." (PMID 38233377, 2024). "In summary, our results demonstrated that 5-FU treatment promotes the degradation of TMPO through autolysosome-related pathway and subsequent activation of c-Fos through ERK1/2 in colon cancer cells, which disclosed a tight negative correlation between TMPO expression and c-Fos activation." (PMID 38233377, 2024).
gastric cancer (3 papers, 2021 to 2024). A primary or metastatic malignant neoplasm involving the stomach. "Studies conducted in gastric cancer patients showed that high levels of thymopoietin were associated with a significantly poorer overall survival, and that knockdown of this hormone suppressed gastric cancer and glioblastoma cell proliferation and survival." (PMID 37529610, 2023). "Additionally, TMPO is highly expressed in gastric cancer and is associated with a poor prognosis, and its knockdown has been demonstrated to reduce the proliferation and invasion of gastric cancer cells." (PMID 38233377, 2024). "TMPO.AS1 performs its tumor-promoting function via activating the PI3K/AKT/mTOR pathway in gastric cancer and HCC." (PMID 34745939, 2021).
glioma (3 papers, 2016 to 2022). A benign or malignant brain and spinal cord tumor that arises from glial cells (astrocytes, oligodendrocytes, ependymal cells). "Although the precise mechanisms are not yet fully understood, this finding suggests that TMPO might play an important role in regulating the proliferation of glioma cells and serve as a new target for GBM treatment." (PMID 27756319, 2016).
lung carcinoma (3 papers, 2016 to 2021).
cardiomyopathy (2 papers, 2020 to 2023). A disease of the heart muscle or myocardium proper. "To further evaluate its role in cardiac muscle, we included TMPO in our cardiomyopathy diagnostic gene panel." (PMID 36672271, 2023). "In particular, although our six patients were men, it cannot be stated that cardiomyopathies related to TMPO mutations will occur exclusively in men." (PMID 36672271, 2023). "Expanded family pedigrees would allow a more accurate assessment of the mode of inheritance and the role of TMPO mutations associated with cardiomyopathies." (PMID 36672271, 2023). "In our study, we noticed that all patients with cardiomyopathy associated with TMPO variants were men." (PMID 36672271, 2023). "Since the only variant reported so far in two DCM siblings, namely LAP2α p.(Arg690Cys), is too prevalent in gnomAD, TMPO has been subsequently excluded from most cardiomyopathy diagnostic gene panels." (PMID 36672271, 2023). "Altogether, our data suggest that TMPO variants might be associated with human diseases, namely cardiomyopathies, which appears as an exciting line of future investigation." (PMID 36672271, 2023). "An analysis of our cohort of ~5000 patients with cardiomyopathies with the targeted gene panel identified three heterozygous TMPO/LAP2α variants (NM_003276.2) with MAF ≤ 0.0027% and classified them according to ACMG guidelines (see Section 2) as pathogenic or likely pathogenic." (PMID 36672271, 2023). "However, all the TMPO pLoF variants in gnomAD show an allele frequency below the threshold (0.01%) used in the context of cardiomyopathy." (PMID 36672271, 2023). "The hypothesis that defects of TMPO, encoding LAP2α,β proteins, could be associated with cardiomyopathy is attractive since LAP2α is a direct partner of lamins A/C." (PMID 36672271, 2023). "Altogether, our observations suggest a role of the three new rare TMPO variants identified in cardiomyopathy patients in altering the properties of LAP2 proteins, and subsequent dysfunction of partners playing a role in chromatin compaction and/or gene expression." (PMID 36672271, 2023). "Finally, our data suggest sex-based differences in LAP2 expression, which might contribute to modulating cardiomyopathy phenotype expression in humans, in accordance with the mice model of TMPO deficiency)." (PMID 36672271, 2023). "The systematic inclusion of TMPO in the cardiomyopathy-targeted gene panels should help us to clarify this point." (PMID 36672271, 2023). "Here, we report (i) the clinical phenotype of six male patients diagnosed of cardiomyopathy (HCM or DCM), harboring three new TMPO variants and (ii) the cellular properties of these new TMPO variants, in comparison with the previously reported p.(Arg690Cys) variant." (PMID 36672271, 2023). "Patient 1 harbors the p.(Gly395Glufs*11) TMPO variant and exome sequencing did not reveal any additional variants that could be involved in the development of cardiomyopathy." (PMID 36672271, 2023). "Furthermore, considering the incomplete penetrance of cardiomyopathy depending on age and sex, some of the gnomAD carriers of pLoF in TMPO might be at an asymptomatic stage of the disease." (PMID 36672271, 2023). "Finally, the fact that mutations of a single gene lead to distinct types of cardiomyopathies is not restricted to TMPO and has been reported for most of the other cardiomyopathy genes." (PMID 36672271, 2023). "Exome sequencing performed on the index patient and his parents (family II) confirmed the maternal inheritance of the TMPO variant but did not reveal any additional pathogenic variant that could explain the cardiomyopathy." (PMID 36672271, 2023). "Whether TMPO is or is not a cardiomyopathy-causing gene was unclear." (PMID 36672271, 2023).
cardiomyopathy (continued). "Thirdly, although exome sequencing has not revealed variants in genes other than TMPO which could explain the cardiomyopathy phenotype in patients, one must keep in mind that the overall diagnostic yield of this technique is typically limited even in familial cardiomyopathies." (PMID 36672271, 2023). "A few lncRNAs are located in the introns of cardiomyopathy-related genes (e.g., TTN, ACTC1, TPM1, JPH2, ANKRD1, DTNA, TMPO, and FHL2) or physically close to these genes." (PMID 32344918, 2020).
diabetes (2 papers, 2022 to 2023). "While FOXP1 was found to be a common interaction partner of PP1MB, SFTPC and TMEM67, an intriguing finding was that the BLM gene was the only common gene among PCa, diabetes mellitus, and obesity, interacting with both FOXP1 and TMPO." (PMID 38235353, 2023).
dilated cardiomyopathy (2 papers, 2018 to 2023). Cardiomyopathy which is characterized by dilation and contractile dysfunction of the left and right ventricles. "The common JAGs responsible for heart diseases included: JARID2 and TBX20, associated with a structural heart anomaly; JAZF1, associated with cardiac tumors; CAMK2G, associated with conduction defects; and CMAK2D and TMPO, associated with dilated cardiomyopathy." (PMID 29449671, 2018).
autoimmune disease (1 paper, 2021). A disorder resulting from loss of function or tissue destruction of an organ or multiple organs, arising from humoral or cellular immune responses of the individual to their own tissue constituents. "Because TMPO rs17028450 was found to be associated with NMOSD, we explored the allele frequencies of this variant in patients with other autoimmune diseases." (PMID 34335680, 2021). "Few non-HLA candidate gene studies have been conducted in NMOSD, and as far as we know, TMPO has not been previously identified as a susceptibility gene in GWAS, nor has it has been studied as a candidate gene for any autoimmune disorder." (PMID 34335680, 2021). "Thymopoietin (TMPO) has not been previously explored as a candidate gene for NMSOD or other autoimmune disease." (PMID 34335680, 2021). "Thymopoietin (TMPO) has not been tested as a candidate gene for NMOSD or other autoimmune disease, however, experimental evidence suggests this gene may be involved in negative selection of autoreactive T cells and autoimmunity." (PMID 34335680, 2021).
breast tumor (1 paper, 2024). "Ankle2, TMPO, Emerin, and Lemd2 were significantly overexpressed in breast tumor samples, in comparison to adjacent normal tissue." (PMID 38720803, 2024).
colitis (1 paper, 2019). Inflammation of the colon. "Remarkably, TP5, a synthetic alternative thymopoietin, dramatically blocked DSS-induced colitis, prevented the body weight loss, and increased the length of the colon and decreased the DAI score." (PMID 31695782, 2019). "It was, therefore, worthwhile to investigate the effect of thymopentin (TP5), a synthetic pentapeptide corresponding to the active domain of the thymopoietin, on colitis." (PMID 31695782, 2019). "This study tried a new therapeutic strategy to combat UC, and found that TP5, a synthetic pentapeptide corresponding to the active site of thymopoietin, made a profound improvement on DSS-induced colitis." (PMID 31695782, 2019).
emotional instability (1 paper, 2023). "Of the six gene scores associated with the emotional instability symptom group, we replicated three genes including IFT74, LDHC and TMPO." (PMID 37322117, 2023).
Ewing sarcoma (1 paper, 2021). A small round cell tumor that lacks morphologic, immunohistochemical, and electron microscopic evidence of neuroectodermal differentiation. "Functionally, FOXP4-AS1 may regulate the malignant phenotype of Ewing sarcoma by upregulating TMPO by sponging miR-298." (PMID 34765540, 2021). "We found that FOXP4-AS1 may regulate the expression of TMPO by sponging miR-298, thereby regulating the malignant phenotype of Ewing sarcoma." (PMID 34765540, 2021). "Therefore, we speculated that FOXP4-AS1 may affect TMPO expression by sponging miR-298, thereby regulating the malignant phenotype of Ewing sarcoma." (PMID 34765540, 2021).
hepatitis B (1 paper, 2022). "Moreover, a synthetic pentapeptide such as thymopentin interacting with the active site in thymopoietin has been found to boost the production of antibodies for hepatitis B vaccines." (PMID 36362351, 2022).
oligodendroglioma (1 paper, 2016). A well-differentiated (WHO grade II), diffusely infiltrating neuroglial tumor, typically located in the cerebral hemispheres. "The French Brain dataset showed that TMPO expression is significantly elevated in oligodendroglioma (n = 23, p = 5.62E−4) compared with the normal tissues." (PMID 27756319, 2016).
ovarian tumor (1 paper, 2021). "Among them, the antisense lncRNA named Thymopoietin (TMPO)-antisense RNA1 (TMPO-AS1) that is known to promote cell proliferation and decrease apoptosis was overexpressed in 5-FU-resistant cells and also in ovarian tumor tissues." (PMID 34204094, 2021).
pancreatic cancer (1 paper, 2024). "Previous investigations have demonstrated TMPO overexpression in multiple tumor cell lines, including breast, colorectal, cervical, and pancreatic cancer models." (PMID 38720803, 2024).
progeria (1 paper, 2024). "TMPO loss in Hutchinson Gilford progeria patient fibroblasts has also been casually linked to a proliferation defect in these cells." (PMID 38720803, 2024).
type 1 diabetes (1 paper, 2021). "Among them, it is known that TMPO is associated with the progression of type 1 diabetes." (PMID 34926685, 2021).